ENSG00000284773 (novel protein)
Gene: Protein-coding gene on chromosome 1 (34,974,356 to 34,985,313, reverse strand). Ensembl gene ENSG00000284773.
Genetic constraint (gnomAD): Loss-of-function variants: 2 observed, 2.19 expected, observed/expected ratio (o/e) 0.91, 90% interval 0.34 to 1.86. That is too few expected variants to judge how well the gene tolerates losing a copy. Missense variants: 55 observed, 45.2 expected, observed/expected ratio (o/e) 1.22, 90% interval 0.98 to 1.52. Synonymous variants: 36 observed, 23.7 expected, observed/expected ratio (o/e) 1.52, 90% interval 1.16 to 1.9.